IL4 (interleukin 4)
Diseases named in the same sentence as IL4 in open-access papers (continued):
Sharing a sentence is not in itself a finding about the gene and the disease.
infection (continued). "BCG-stimulated splenocytes displayed notably low concentrations of TH2 (IL-4 and IL-13) cytokines in all infection groups." (PMID 24433309, 2014). "The Th2 cytokines IL-5 and IL-13 increased steadily from week 2 onwards; IL-4 was only increased late in infection." (PMID 25398130, 2014). "We found that saliva does indeed enhance infection levels of vector-transmitted pathogens and leishmaniasis pathology in naïve mice and elevates Th2 cytokine levels (IL-4 and IL-10)." (PMID 25275509, 2014). "IFN-γ/IL-4 ratios were calculated as an indicator of the balance of the Th1/Th2 cellular immune responses throughout the infection." (PMID 24479988, 2014). "For TH2 and TH17 regulatory cytokines, significant differences in the serum concentrations of IL-4 (P = 0.0086) and IL-10 (P = 0.0297) were detected between the primary and the secondary infections." (PMID 25295285, 2014). "Compared to their wild type counterparts, NKT cell-deficient mice on a C57BL/6 background were better able to contain infection with L. major and showed decreased IL-4 production in cytokine analysis performed 5 and 8 weeks after infection." (PMID 24967701, 2014). "This high diversity and upregulation by IL-4 strongly suggests CLPs are involved in protection against infection, and the fundamental mechanism of action is likely to be shared across species." (PMID 25319331, 2014). "When injected intravenously, the enhancing effect on the infection of Leishmania extracts depends on the presence of IL-4." (PMID 24484604, 2014). "There were also significantly reduced eosinophil numbers (P < 0.05), IFN-γ levels (P < 0.01), and IL-4 levels (P < 0.01) in the airways on day 4 after infection." (PMID 24173217, 2014). "Primary and secondary infection with H. polygyrus promotes a T-cell-dependent IgE response, which requires IL-4 signaling in vivo." (PMID 24185641, 2014). "The infection induced a significant increase of IL-4 and IL-10 in serum and the culture of splenocytes, whereas, OVA induced a significant increase of IL-17A in serum and splenocyte supernatants compared with in the PBS control mice." (PMID 25409540, 2014). "Lower levels of IFN-γ were detected at week 2 of infection in both mouse strains treated with 1MT, but IL-12, IL-4 and IL-10 appeared in lower levels only in B10.A treated mice." (PMID 25411790, 2014). "Significant Th2-type responsiveness was seen from week 7 of infection onwards, after the onset of oviposition, with IL-4 and IL-5 rising ahead of IL-13." (PMID 25398130, 2014). "Contrast to IFN-γ+ CSCs increasing from the early infection, IL-2+ and IL-4+ CSCs only increased 12 days post infection, which implied the strongly stimulated adapted immune response." (PMID 24725777, 2014). "For the regulatory cytokine IL-10, and for the TH2 and TH17 cytokines such as IL-4, IL-6, and IL-17, our results indicate significant differences when comparing all primary infections with Leishmania spp." (PMID 25295285, 2014). "Taken together, these data suggest that the discordant regulation of interferon and IL-4 pathway genes by EBV that occurs early following infection of B cells has relevance to the development or maintenance of an EBV-associated malignancy." (PMID 23724103, 2013). "IL-4, as a cytokine produced by Th2 cells, plays a crucial role in promoting host survival during infection with parasitic helminthes." (PMID 24308005, 2013). "In contrast, a higher production of IL-4 in response to S. rotundus than in response to S. rugosus was observed only at days 15 post-infection." (PMID 23555735, 2013). "In the case of Nippostrongylus brasiliensis infection, macrophage accumulation starts at day 4 post infection (PI) and precedes the peak IL-4/13 expression at day 7 PI and maximal gut functional alterations at day 9 PI." (PMID 23536877, 2013).
infection (continued). "Accordingly, IL-4−/− BALB/c mice are able to control infection with some Leishmania major strains at least partially and BALB/c mice treated with anti-IL-4 Ab at the time of challenge exhibit a healing phenotype." (PMID 23825956, 2013). "As IL-4 mRNA levels are significantly lower in CD4+ T cells from WSX-1−/− mice than from WT mice on day 13 of infection our results suggest that the transition from Th1 to Th2 based immunity does not occur in WSX-1−/− mice during malaria infection." (PMID 23593003, 2013). "In the context of infection, many pathogens induce IL-4 that serves to ‘deviate’ immunity away from an anti-microbial Th1 response." (PMID 23991011, 2013). "At the peak of infection, mice were sacrificed, spleens and draining lymph nodes removed and analyzed for the production of IL-4." (PMID 23437409, 2013). "On day 14 days post infection the key Th2 cytokines IL-4 and IL-13 as well as anti-inflammatory IL-10 were produced in significantly higher amounts by mLN cells from infected mice in response to mitogen and parasite antigen." (PMID 24040152, 2013). "We show that during infection with L. major, enhanced Arginase-1 in MKP-2 deficient mice serves to induce a generalized T cell hypo-responsiveness so that IFN-γ and IL-4 levels are equally suppressed compared with intact mice." (PMID 23437409, 2013). "We were able to confirm in many cases that the induction by EBV of those ISGs that were differentially expressed in EBV blasts was reduced following infection in the presence of IL-4." (PMID 23724103, 2013). "Initially, at day 14 post infection, there is a large percentage of cells expressing IL-4, which then decreased at days 28 and 42 post infection." (PMID 24205367, 2013). "After REV infection, the expression levels of Th2 and regulatory cytokines (IL-4、IL-10 and IL-13) were drastically increased after 7 dpi, and moderately increased at 14 days and then up-regulated after 21 and 28 days following infection." (PMID 24358317, 2013). "Several reports have also shown that a variety of proinflammatory cytokines can overcome Treg suppression during infection or in an inflamed environment, including IL-2, IL-4, IL-6, and TNF-α." (PMID 23593527, 2013). "Here, the significantly higher intestinal worm burden at day 5 secondary infection in IL-13−/− mice compared to IL-4−/− mice, demonstrated IL-13 signalling through IL-4Rα is essential for immunity against re-infection with N. brasiliensis." (PMID 24204255, 2013). "M2a MDM derived by IL-4 treatment express DC-SIGN that facilitates cis infection with both R5 and X4 HIV-1 and subsequent efficient trans infection of T cells." (PMID 24278768, 2013). "VV-HA-IL-4 infection studies showed that IL-4 and STAT6 was required to up-regulate IL-4Rα expression on naïve and effector CD8+ T cells." (PMID 23383283, 2013). "Using Leishmania major infection to test the biological significance of changes in IL-4, we found that blocking IL-4 during infection also led to an increased number of IFNγ-producers in the infected dermis and improved pathogen control." (PMID 23991011, 2013). "We examined profile of IFN-γ, a pathogenic Th1 cytokine of ECM, IL-4, a Th2 cytokine, TGF-β and IL-10, regulatory cytokines during the first week of infection." (PMID 23724100, 2013). "For example, in a recent study it was shown that after infection causing a Th1 or Th2 response, most T cells in a draining lymph node were exposed to activating amounts of IFN-γ or IL-4, respectively." (PMID 23935451, 2013). "The colonic gene expression of IL-10, IL-12p35, and IL-4 remained suppressed throughout the duration of infection alluding to the limited impact of colonic Treg, Th1, and Th2 cells in this process." (PMID 23469071, 2013). "Infected neonatal mice had significantly elevated IL-4 and IL-10 production compared to infected adults 28 days post infection (P = 0.0248, 0.0434 respectively)." (PMID 24376704, 2013).
infection (continued). "Conjunctival gene expression profiling in children with active disease and Ct infection found an increase in both Th1 (IFNγ) and Th2 (IL-4) cytokine expression." (PMID 23457650, 2013). "By 8 weeks of infection, the production of IL-4 and other TH2 cytokines predominates and IFNγ is barely detectable." (PMID 23429492, 2013). "IL-27 does not appear to regulate the initial priming or differentiation of Th1 cells during infection, unless IL-4 is present, when IL-27 is required to limit Th2 differentiation and enable Th1 responses to develop." (PMID 23593003, 2013). "Experimental murine infection has proven that increased production of IL-4 during the chronic phases of infection is characterized by progressive fibrosis and necrosis." (PMID 23144845, 2012). "Cytokines profiles demonstrated an expected finding that IL-4, commonly expressed in helminth and fungus infection, is undetectable in the two infection groups." (PMID 23285072, 2012). "It is well established that IL-4 exacerbates leishmaniasis when added exogenously, and IL-10 mutant mice become resistant to infection." (PMID 22448168, 2012). "In this study the plasma levels of three proinflammatory (TNF-α, IFN-γ, IL-4) and one anti-inflammatory cytokine (IL-10) during a primary infection with Mycoplasma mycoides subsp." (PMID 22533922, 2012). "In a mouse model, treatment with anti-IL-4 and anti-IL-5 antibodies resulted in an increased level of infection compared to isotype antibody control animals." (PMID 22685452, 2012). "In vivo, infection with PR8 virus stimulated IL-4 secreting cells in the spleen of mice vaccinated with both H5N1-VLP and H5M2eN1-VLP (post-D4)." (PMID 22879951, 2012). "In contrast, other laboratories have shown that production of IL-4 aids in clearance of LVS infection and that LVS can inhibit inflammation mediated, in part, by IL-4." (PMID 22428026, 2012). "It is important to note that the resistance-promoting role of IL-4 was only achieved when IL-4 was strictly present during the initial activation of DC upon infection." (PMID 22802978, 2012). "Infection of BALB/c mice with L. major induces early production of IL-4 by CD4+ T cells carrying the Vβ4α8 T cell receptor at 16 h after infection." (PMID 22838729, 2012). "They showed that RSV-infection of epithelial cells reduces epithelial-mediated T cell suppression similar to the effects, we observed for treatment of epithelial cells with IL-4." (PMID 23029313, 2012). "In this study, we used the ELISPOT assay to detect and enumerate cells producing IFN-γ and IL-4 to evaluate the influence of type 1 and type 2 T-cell cytokines during infections and/or aGVHD." (PMID 24710414, 2012). "Production of histamine and IL-4 detected in skin biopsies immediately after the last infection of re-infected mice was realized via IgE-dependent mast cell degranulation." (PMID 23125918, 2012). "The lesion size in EA-treated mice was more pronounced than that in sham-treated mice, suggesting that EA increases IL-4 responsiveness in vivo and interferes with the outcome of infection by intracellular pathogens such as L. major." (PMID 22838729, 2012). "IL10 followed a similar pattern with a small delay while IL4 slowly increased and peaked 60 days post infection." (PMID 22253585, 2012). "The IL-4 level was much higher in pre-infected water buffalo than in yellow cattle, but subsequently the cytokine decreased to a very low level at 2w post infection, increased at 4w and decreased at 7w post infection in water buffalo." (PMID 22414188, 2012). "Following the infection, IFNγ rapidly peaked after two time steps while IL4 and IL10 activation followed with a delay, in line with empirical findings." (PMID 22253585, 2012). "As shown after low dose infection with L. major, enhanced IL-4 expression is followed by a compensatory IFNγ response by CD8 cells." (PMID 23028548, 2012).
infection (continued). "The IL-4 concentration increased post infection from zero up to 340 pg/ml before dropping to 100 pg/ml before euthanasia." (PMID 22533922, 2012). "Dendritic cells also activated the Th2 cell mediated expression of IL4 and as this arm of the immune response developed, IFNγ decreased although remained in an active state throughout the infection." (PMID 22253585, 2012). "This outcome was associated with increased expression of IFN-γ and down regulation of IL-4 at the infection site." (PMID 23284976, 2012). "CAPN14 is up-regulated in human conjunctival epithelial cells by interleukin-4, a key T helper 2 cytokine involved in infection control and allergic responses." (PMID 23133572, 2012). "This differs from increase of serum levels of IL-4, IFNγ and IL-12 observed in CcS/Dem strains after 8 weeks of infection." (PMID 22679519, 2012). "IL-4-deficient (IL-4−/−), as well as IL-4 receptor alpha (IL-4Rα)-deficient BALB/c mice are resistant to infection with L. major." (PMID 22802978, 2012). "Production of IL-4 and IL-10 was statistically significant in infected animals at day 2 post-infection compared to their secretion preinfection (P < 0.05)." (PMID 22340040, 2012). "Our results extend these findings by showing that upon immunization with IL-4-responsive DC, higher percentages of activated and mature recipient DC are observed in the lymph nodes draining the site of infection." (PMID 22802978, 2012). "The detection of IL-4 in the liver tissue by ELISA was also significantly higher in WT mice compared to Jα18-/- mice on D30 (p<0.05) and D60 post-infection (p<0.01)." (PMID 22457760, 2012). "Very interestingly, H-1 PV is even able to enhance activated CD4+ T cell ability to release IL-2 right from the beginning of the infection, and IL-4 at early and late infection stages (24 h and 120 h after the inoculation)." (PMID 22359669, 2012). "Immunity to secondary infection is diminished by blocking antibody to IL-4 but completely abolished when the IL-4R is also blocked." (PMID 23053394, 2012). "The IL-4 level was high in pre-infected water buffalo, then decreased post infection, and was at a very low level 7w post infection." (PMID 22414188, 2012). "The overall expression of IL4 was lower in co-infected individuals (P = 0.035), however higher values were observed at 14 days post infection (interaction of IL4 with day 14 post infection P = 0.046)." (PMID 22253585, 2012). "CD4 T-cells with a Th2 phenotype have been proposed to overall suppress inflammation and demyelination: IL-4 treatment during the early chronic phase of TMEV infection resulted in a more benign disease phenotype, with reduced anti-TMEV antibody responses." (PMID 22348089, 2012). "After systemic infection with L. donovani, a relatively silent phase during the first ∼3 weeks of infection was followed by increased expression of IL-4, IL-10, IL-13, and IL-21." (PMID 22275864, 2012). "Sera IL-4 levels were significantly higher in the pAg85A‐sHA2 group or the pHA vaccinated group than those in the psHA2 group on Day 12 after infection with the PR8 virus (P < 0.05)." (PMID 23223215, 2012). "CD8+ lymphocytes have been reported in different human infections to secrete inhibitory cytokines, such as IL-10 or IL-4, and CD8+CD25+ regulatory T cells have also been reported to suppress the CD4+ T-cell-mediated IFN-γ production and proliferation." (PMID 22550536, 2012). "Using IL-4- and IL-13-reporter mice to track these cells, a dominant IL-13-producing, innate cell population (nuocytes) expanded in response to the infection, similar to that seen after injection of IL-25 or IL-33." (PMID 22360486, 2012). "The level of IL-4 was very low pre-infection and at 2w post infection in yellow cattle, and a low IL-4 level was detected at 4w and 7w in yellow cattle challenged with schistosomes." (PMID 22414188, 2012). "When both PPAR/RXR ligands were coadministered, the degree of infection was similar to those infected in the presence of IL-4." (PMID 22448168, 2012).
infection (continued). "The proportion of intracellular cytokines IFN-γ and IL-4 produced by peripheral blood cells in yellow cattle and water buffalo pre and post infection with S. japonicum were detected." (PMID 22414188, 2012). "After infection with H. suis, expression of IL-4, a marker of a Th2 response, was higher in the lysate-immunized group than in groups vaccinated with rUreB and rNapA." (PMID 23101660, 2012). "Comparing with water buffalo, the IFN-γ level was higher and decreased significantly, while the IL-4 level was lower and increased gradually in yellow cattle from pre-infection to 7 w post infection." (PMID 22414188, 2012). "Collectively these data demonstrate that upon infection with L. mexicana, initial lesion growth in BALB/c mice is dependent on non-T cell population(s) responsive to IL-4/IL-13 while progressive infection is dependent on CD4+ T cells responsive to IL-4." (PMID 21245915, 2011). "Since HPB regimen showed higher IL-4 after vaccination, and substantially lower IL-4 after challenge infection, early mixed Th1/Th2 responses exhibited by this groups of mice was therefore skewed in Th1 biased response after L. donovani infection." (PMID 21311597, 2011). "For example, acute infection of C57BL/6 mice with a high dose (200 eggs) of Trichuris results in a polarized Th2 cell response, characterized by high levels of IL-4, IL-5 and IL-13, and resistance to infection." (PMID 21573179, 2011). "The finding that Nippo mice have higher intraperitoneal IL-6 levels 4 h after infection and that IL-4-conditioned mast cells generate more IL-6 is consistent with the idea that mast cells are a source of the higher IL-6 levels in Nippo mice." (PMID 22110673, 2011). "Using this model, we show that immunomodulation by IL-4 contributes to the different disease outcomes observed upon infection with different L. braziliensis isolates." (PMID 21390155, 2011). "A recent study demonstrated that infection of mice with lymphocytic choriomeningitis virus reprogrammed otherwise stably committed Th2 cells to adopt an IL-4+IFNγ+ “Th2+1” phenotype that was maintained in vivo for months." (PMID 21533073, 2011). "Based on the important roles contributed to these cytokines, we investigated the levels of IFN-γ, IL-12 (p40), (Th1 cytokines) and IL-4, IL-10 (Th2 cytokines) after 3 months of infection." (PMID 22206029, 2011). "Consistent with this, intestinal gene expression levels of Il4, Il5 and Il13 at day 14 post-infection were heightened in CD103−/− mice." (PMID 21573179, 2011). "To examine transcriptional changes in networks associated with host protective immunity during HN878 infection, we evaluated the differential expression of genes involved in the IFN-γ, IL-4 and T- and B-cell activation networks." (PMID 22645653, 2011). "It was also co-incident with increased antigen-specific mLN cell proliferation and IL-4 production at the chronic phase of infection." (PMID 21858239, 2011). "Th2 cytokines such as IL-4 and IL-13 are strongly up-regulated during a primary infection while TNFα and IFN-γ remains largely unchanged." (PMID 21414188, 2011). "In the present study, we described that the injection of CFA prior to infection induced a Th2 profile, increasing IL-4 levels in the lung, liver and spleen homogenates, and decreased the IFN-γ production when compared with only Pb-infected mice." (PMID 21731741, 2011). "TLR7-/- MDSCs, when compared to B6, not only show increased recruitment to the site of infection and secrete increased amounts of Th1 inhibiting IL-10 in vivo, but also increase the amount of IL-4 production from OT-II T-cells." (PMID 21966467, 2011). "In this way, IL4 SNPs can effectively influence the intensity of various infections, including enteric pathogens." (PMID 21501512, 2011). "The proposed difference in findings was suggested to be due to removal of the cytokines GM-CSF and IL-4 from DCs upon infection with Mtb." (PMID 22024399, 2011).